MIR3617 (microRNA 3617)
Synonyms: hsa-mir-3617
Gene: MicroRNA gene on chromosome 20 (45,705,102 to 45,705,180, reverse strand). Ensembl gene ENSG00000266071.
Homologues: Orthologues: chimpanzee MIR3617 (100% identical).